S1PR3 (sphingosine-1-phosphate receptor 3)
Diseases named in the same sentence as S1PR3 in open-access papers (continued):
Sharing a sentence is not in itself a finding about the gene and the disease.
malaria (4 papers, 2019 to 2022). Malaria is a serious and sometimes fatal disease caused by a parasite that commonly infects a certain type of mosquito which feeds on humans. "Further studies should focus on the mechanism of particular cell types with increased expression of SphK1 and S1PR3 during pulmonary edema caused by malaria." (PMID 32185202, 2020). "Although increasing evidence suggests the involvement of S1P in malaria, very little is known regarding the role of SphK-1 and S1PR-3 in malaria-associated ALI/ARDS." (PMID 31483837, 2019). "We hypothesized that S1P might mediate ALI/ARDS via a signalling pathway involving the conversion of sphingosine to S1P by SphK-1; then, binding of S1P to S1PR-3 leads to receptor activation that promotes the development of malaria-associated ALI/ARDS." (PMID 31483837, 2019). "Therefore, our findings confirmed that high S1PR-3 expression is associated with the development of malaria-associated ALI/ARDS in mice." (PMID 31483837, 2019). "A recent study revealed that the SphK-1 and S1PR-3 expression levels were significantly upregulated in the lung tissues of malaria-infected mice with ALI/ARDS." (PMID 32185202, 2020). "Over expression of both SPHK-1 and S1PR-3 proteins were observed in lung tissues of PE indicating their role in the pathogenesis of pulmonary complications in severe malaria." (PMID 32923406, 2020). "In conclusion, both the SphK-1 and S1PR-3 proteins were overexpressed in the lung tissues of severe P. falciparum malaria patients with PE, suggesting that SphK-1 and S1PR-3 mediate the pathogenesis of PE in severe malaria." (PMID 32185202, 2020). "First, the specimens used in this study were lung tissues from autopsied malaria patients that had been stored for approximately 30 years and were thus unsuitable for determining the gene expression levels of SphK-1 and S1PR-3 via molecular techniques." (PMID 32185202, 2020). "The measurement of sphingosine and ceramide levels should be determined in the lung tissue and plasma samples to explain the functional role of SphK-1/S1P /S1PR-3 pathway involved in the pathogenesis of malaria." (PMID 31483837, 2019). "Moreover, further studies of S1PR-3 antagonists/blockers in malaria-infected mice with ALI/ARDS would help to confirm the involvement of S1PR-3 and SphK-1 in malaria-infected mice with ALI/ARDS." (PMID 31483837, 2019). "Furthermore, increased expression of the SphK-1 and S1PR-3 proteins significantly correlated with lung injury scores and S1P concentrations in malaria-infected mice with ALI/ARDS." (PMID 31483837, 2019). "Finally, to definitely demonstrate how SphK-1 and S1PR-3 are involved in malaria-associated ALI/ARDS, global gene expression analysis should be performed to identify the signalling pathways involved with SphK-1 and S1PR-3." (PMID 31483837, 2019). "The results demonstrated that the cellular expression of the SphK-1 and S1PR-3 proteins was significantly upregulated in endothelial cells, alveolar epithelial cells and alveolar macrophages in the lung tissues of malaria-infected mice with ALI/ARDS compared with those in the control groups." (PMID 31483837, 2019). "In addition, strong immunoreactivity of S1PR-3 expression was evident in endothelial cells, alveolar epithelial cells and alveolar macrophages in the lung tissues of malaria-infected mice with ALI/ARDS." (PMID 31483837, 2019). "The present study indicated that liver tissue from malaria-infected mice has decreased expression of S1PR1, S1PR2, and S1PR3 and increased expression of SphK1." (PMID 35333897, 2022). "Therefore, S1PR-3 might affect the pathogenesis of PE in malaria." (PMID 32185202, 2020). "In malaria-infected mice with ALI/ARDS (n = 10), there was a positive correlation between the total score of SphK-1 and S1PR-3 expression levels in endothelial cells (Spearman’s rank correlation, rs = 0.997; p < 0.001)." (PMID 31483837, 2019).
malaria (continued). "This study did not determine the level of S1PR-3 in plasma; therefore, we could not demonstrate the time course of S1PR-3 expression in malaria-infected mice with ALI/ARDS." (PMID 31483837, 2019).
myocardial infarction (4 papers, 2018 to 2024). Gross necrosis of the myocardium, as a result of interruption of the blood supply to the area, as in coronary thrombosis. "S1PR3 mediated the cardioprotective effects of HDL in an in vivo mouse model of myocardial infarction." (PMID 38675158, 2024).
renal cell carcinoma (4 papers, 2021 to 2023). "Interestingly, a study has also reported that EGR2 could increase IGF2BPs expression to enhance the m6A level of sphingosine-1-phosphate receptor 3 to accelerate tumorigenesis and metastasis of renal cell cancer." (PMID 37529797, 2022). "Our studies showed that the EGR2/IGF2BPs regulatory axis and m6A-dependent regulation of S1PR3-driven RCC tumorigenesis, which enrich the m6A-modulated regulatory network in renal cell cancer." (PMID 34326314, 2021).
cerebral infarction (3 papers, 2018 to 2023). An ischemic condition of the brain, producing a persistent focal neurological deficit in the area of distribution of the cerebral arteries. "S1PR3 antagonists have been shown to provide protective effects in various neurological injuries, including cerebral infarction and spinal cord injury." (PMID 37409121, 2023). "In-depth studies of S1PR3 as a new target for the development of a therapeutic paradigm and the possibility of discovering new drugs for cerebral infarction will be very important and helpful." (PMID 35685645, 2022). "S1PR3 also represents a potential predictor of cerebral infarction." (PMID 35685645, 2022).
endothelial dysfunction (3 papers, 2019 to 2022). In vascular diseases, endothelial dysfunction is a systemic pathological state of the endothelium (the inner lining of blood vessels) and can be broadly defined as an imbalance between vasodilating and vasoconstricting substances produced by (or acting on) the endothelium. "Taken together, these results show that Smyd2 enhances Sphk and S1PR3 expression and negatively regulates S1PR1 expression, resulting in endothelial dysfunction." (PMID 35297562, 2022).
fibrosis (3 papers, 2014 to 2025). the formation of excess fibrous connective tissue in an organ or tissue in a reparative or reactive process. "When these mice were crossed with S1PR3-deficient mice, the ability of SphK1 overexpression to produce cardiac fibrosis was diminished, suggesting that the pro-fibrotic effects of S1P in the heart are at least partially mediated by S1PR3." (PMID 38015241, 2024).
Hepatic steatosis (3 papers, 2022 to 2023). Steatosis is a term used to denote lipid accumulation within hepatocytes. "This worsened metabolic phenotype of HFD-fed S1PR3-/- mice was mechanistically linked with increased adipose inflammation, adipose macrophage and T-cell accumulation, hepatic inflammation and hepatic steatosis." (PMID 35094654, 2022). "In our study, increased hepatic steatosis in HFD-fed S1PR3−/− mice was mechanistically related to elevated expression of CD36, a fatty acid transporter and the lipogenic transcription factor SREBP1c." (PMID 35094654, 2022). "We therefore next determined how the expression of S1PR3 is regulated in the livers of HFD-induced obese mice and its role in hepatic steatosis and inflammatory pathways." (PMID 35094654, 2022). "The exacerbated hepatic steatosis and inflammation observed in HFD-fed S1PR3−/− mice above what was observed for HFD-fed WT mice suggests that S1P-S1PR3 signalling confers protection from lipid accumulation and inflammation in the liver." (PMID 35094654, 2022).
leukemia (3 papers, 2021 to 2023). A malignant (clonal) hematologic disorder, involving hematopoietic stem cells and characterized by the presence of primitive or atypical myeloid or lymphoid cells in the bone marrow and the blood. "In one report, it was found that S1PR3 overexpression in HSCs induced leukemia, pointing to high S1PR3 as an AML-inducing factor and a potential target for therapy." (PMID 36361536, 2022). "While investigational efforts were more focused on the role of S1PR3 in leukemia and myelopoiesis, the study found that S1PR3 over-expression in human HSCs favored CD33+ myeloid and CD41+ megakaryocytic lineage commitment at the expense of erythroid and lymphoid lineage commitment." (PMID 34685487, 2021).
osteoporosis (3 papers, 2014 to 2025). A condition of reduced bone mass, with decreased cortical thickness and a decrease in the number and size of the trabeculae of cancellous bone (but normal chemical composition), resulting in increased fracture incidence. "For instance, S1PR3 agonists have been shown to enhance bone formation by promoting osteoblast differentiation, whereas S1PR2 antagonists may suppress bone resorption, offering targeted strategies for osteoporosis management." (PMID 41367909, 2025).
Paget disease (3 papers, 2021 to 2025). A malignant neoplasm composed of large cells with large nuclei, prominent nucleoli, and abundant pale cytoplasm (Paget cells). "The authors concluded that when combined, and via the upregulation of Ephrin (Eph) B2 and EphB4 in osteoclasts and osteoblasts, respectively, increased S1P via S1PR3 signaling resulted in the displayed increase in bone formation observed in Paget’s disease." (PMID 38474268, 2024). "Model for the effects of sphingosine kinase‐1/sphingosine‐1‐phosphate/S1P‐receptor‐3 (SphK‐1/S1P/S1PR3) in abnormal bone remodeling in Paget's disease (PD)." (PMID 33107091, 2021). "Moreover, in Paget’s disease, S1PR3 antagonists might help mitigate excessive bone formation." (PMID 41367909, 2025). "The study identified a Paget’s disease-induced increase in IL-6 production by osteoclasts, subsequently increasing S1P secretion, which, together with IGF-1, promoted S1PR3 expression in osteoblasts to promote bone formation." (PMID 38474268, 2024).
brain tumor (2 papers, 2023 to 2024). "S1PR1, S1PR2 and S1PR3 were shown to be elevated in patient brain-tumor samples compared to normal brain samples, and Kaplan–Meier analyses have demonstrated an association between S1PR1 and S1PR2 with patients’ survival times." (PMID 37686550, 2023). "CNV events affecting these three likely pathogenic mutations, GNAQ R183Q, S1PR3 G89S, and NRAS G12V, were observed exclusively in abdominal and brain tumor samples and not detected in the cerebral cortex, white matter, or skin." (PMID 38254245, 2024).
cardiac hypertrophy (2 papers, 2017 to 2025). "Activation of S1PR3, which couples to Gq and G12/13 unlike S1PR1, might lead to cardiac fibrosis without hypertrophy." (PMID 28771545, 2017).
gastric cancer (2 papers, 2016 to 2021). A primary or metastatic malignant neoplasm involving the stomach. "While bound to S1PR3, S1P promoted gastric cancer cell (MKN1 and HCG-27, predominantly expressed S1PR3) migration." (PMID 34831211, 2021).
hepatocellular carcinoma (2 papers, 2020 to 2023). A malignant tumor that arises from hepatocytes. "It has been shown in some studies that the S1PR2/S1PR3 axis regulated Na+/K+ ATPase in the hepatocellular carcinoma cell line, while others have indicated that Na+/K+ ATPase might serve as an alternative for V-ATPase in astrocytes." (PMID 36719377, 2023).
Hyperglycemia (2 papers, 2019 to 2024). An increased concentration of glucose in the blood. "Hyperglycemia also increases intrahepatic S1P and S1PR3 levels both in patients and experimental animals." (PMID 31798592, 2019).
lymphangioleiomyomatosis (2 papers, 2023 to 2025). A multifocal neoplasm with perivascular epithelioid cell differentiation affecting almost exclusively females of child-bearing age. "In lymphangioleiomyomatosis, activated SphK1/S1P/S1PR3 signaling promotes mTORC1 activation and autophagy suppression, reducing tumor cell survival, migration, and invasion." (PMID 40906080, 2025). "SphK1/S1P/S1PR3 signaling is activated in Lymphangioleiomyomatosis (LAM), leading to mTORC1 activation and autophagy inhibition." (PMID 37852968, 2023).
lymphoma (2 papers, 2016 to 2023). A malignant (clonal) proliferation of B- lymphocytes or T- lymphocytes which involves the lymph nodes, bone marrow and/or extranodal sites. "Three S1PR inhibitors (W146 for S1PR1, CAY10444 for S1PR3, and FTY720 for S1PR1–5) were selected to demonstrate the hypothesis that S1P signaling could mediate the HIPPO pathway in lymphoma cells." (PMID 36600310, 2023).
melanoma (2 papers, 2016 to 2020). A malignant, usually aggressive tumor composed of atypical, neoplastic melanocytes. "In melanoma tumors, dysregulation of S1P production in cancer cells elicits a fibrotic response in the tumor microenvironment, which in turn stimulates melanoma cell migration by promoting S1PR3 expression." (PMID 27708249, 2016). "Since S1PR1, 2 and 3 are expressed by BMDM, we next examined whether S1PR1 and S1PR3, which are known to promote cell migration, are implicated in BMDM migration upon incubation with melanoma CM." (PMID 27708249, 2016).
ocular adnexal lymphoma (2 papers, 2015 to 2022). A non-Hodgkin lymphoma arising from the conjunctiva, lacrimal gland, lacrimal drainage apparatus, eyelids, or other orbital tissues around the eye. "In fact, patient samples of lymphomas from secondary lymphoid organs (SLOs) had higher expression of S1PR2, while samples from ocular adnexal lymphomas (OAL) had higher S1PR3 expression." (PMID 36361536, 2022). "In contrast, the malignant B cells in ocular adnexal lymphomas (10 FL, 9 DLBCL, 4 MCL and 28 MZL) expressed a profile of molecules suggesting a dynamic process of trafficking involving not only tissue retention but also egress via S1PR3 and homing back to extranodal sites via CXCR4/CXCL12 and α4." (PMID 25938000, 2015).
renal carcinoma (2 papers, 2021 to 2024). A carcinoma arising from the epithelium of the renal parenchyma or the renal pelvis. "For example, EGR2 can drive renal cancer occurrence and metastasis by enhancing S1PR3 mRNA stability." (PMID 38911380, 2024). "Furthermore, WTAP/m6A/IGF2BPs/S1PR3 regulated renal cancer proliferation and metastasis in a PI3K/AKT-dependent pattern." (PMID 34326314, 2021).
steatosis (2 papers, 2022 to 2023). Increased lipid within the cytoplasm of cells. "S1PR2 signaling has been demonstrated to drive NASH, while genetic S1PR3 ablation predisposes HFD-fed mice to inflammation/steatosis." (PMID 36719377, 2023). "Steatosis was dramatically increased in HDF-fed S1PR3−/− mice when compared with HFD-WT counterparts." (PMID 35094654, 2022). "HFD-fed S1PR3−/− showed a fat distribution that resembled a phenotype of partial lipodystrophy with redistribution of lipids from AT to the liver resulting in decreased EAT weight with increased liver weight and steatosis." (PMID 35094654, 2022).
abdominal aortic aneurysm (1 paper, 2022). Enlargement and ballooning of the vessel that supplies arterial blood to the abdomen, pelvis and legs. "Through chemotaxis and PGE2 production, S1PR3 may play a role in the severe inflammation observed in the course of abdominal aortic aneurysms and atherosclerosis." (PMID 35745168, 2022). "In the abdominal aortic aneurysm, it was shown that the level of S1PR2 decreases, while the amount of S1PR3 increases compared to the control tissue." (PMID 35745168, 2022).
acute promyelocytic leukemia (1 paper, 2009). An aggressive form of acute myeloid leukemia (AML), characterized by arrest of leukocyte differentiation at the promyelocyte stage, due to a specific chromosomal translocation t(15;17) in myeloid cells. "It is postulated to be a target gene in all-trans-retinoic acid (RA) treatment of acute promyelocytic leukemia, where as sphingosine-1-phosphate receptor 3 belongs to the EDG (endothelial differentiation gene) receptor family of g protein coupled receptors." (PMID 19812696, 2009).
bacterial sepsis (1 paper, 2020). "For infectious diseases, elevated expression of S1PR-3 was found in monocytes from patients with bacterial sepsis and in CD4−CD8− T cells during the acute phase of Trypanosoma cruzi infection." (PMID 32185202, 2020). "Finally, there might be other unidentified factors involved in the increased expression of S1PR-3, such as bacterial sepsis." (PMID 32185202, 2020). "Although, no bacterial sepsis was recorded among the enrolled patients, during the treatment period in the past, unrecognized bacterial sepsis may have occurred; thus, this parameter might be one possible confounding factor of the elevated expression of S1PR-3 in our study." (PMID 32185202, 2020).
bladder cancer (1 paper, 2024). "as it was reported that the expression of S1P receptors, S1PR1, S1PR2 and S1PR3 is linked to the pathological grades and stages of bladder cancer." (PMID 39315290, 2024).
bone cancer (1 paper, 2018). A primary or metastatic malignant neoplasm affecting the bone or articular cartilage. "Likewise, one study found that intrathecal fingolimod reduces bone cancer pain, and while analgesia was attributed to effects on S1PR1 in glia, some of the benefits may be due to S1PR3 signaling in DRG neurons." (PMID 29561262, 2018).
diabetic nephropathy (1 paper, 2013). "For example, S1PR3 is related to fibrosis in cardiac ventricular fibroblasts, S1PR2 is involved in a diabetic nephropathy model, and a relationship has been found between S1PR3 and fibrosis in myofibroblasts." (PMID 24744854, 2013).
Duchenne muscular dystrophy (1 paper, 2013). Duchenne muscular dystrophy (DMD) is a neuromuscular disease characterized by rapidly progressive muscle weakness and wasting due to degeneration of skeletal, smooth and cardiac muscle. "Importantly, genetically deleting S1PR3 in the mdx mouse model of Duchenne muscular dystrophy produced a less severe muscle dystrophic phenotype, than when signalling though S1PR3 was operational." (PMID 23911934, 2013). "To also examine the effects of a lack of S1PR3 signalling on chronic muscle regeneration, we examined the dystrophic phenotype in the mdx mouse model of Duchenne muscular dystrophy." (PMID 23911934, 2013). "We also used the mdx mouse model of Duchenne muscular dystrophy to investigate if the absence of S1PR3 improved chronic muscle regeneration, and found that the dystrophic muscle phenotype was less severe in S1PR3−/−/mdx mice." (PMID 23911934, 2013).
gastric ulcer (1 paper, 2014). An ulcerated lesion in the mucosal surface of the stomach. "Our results show that CA can decrease the expression of S1P and its receptors, including S1Pr1 and S1Pr3, to relieve inflammation problems to relieve the formation of gastric ulcers." (PMID 24454691, 2014).
hyperreactivity (1 paper, 2017). "The sphingosine 1-P receptor, S1pr3, was very highly expressed especially in nodose neurons, and S1pr3 activation has recently been implicated in the vagal C-fiber involvement of airways hyperreactivity associated with allergic airway inflammation of the mouse." (PMID 28982197, 2017).
inflammatory skin disease (1 paper, 2023). Inflammatory skin disorders covers a broad category that includes many conditions ranging in severity, from mild itching to grave medical health complications These disorders are common in people of all ages and races. "Particularly, subtype-specific agonists and antagonists help to further understand the complex role of S1P signaling, and it seems promising to further elucidate these roles, especially the role of S1PR2 and S1PR3 in inflammatory skin diseases and itch." (PMID 36674974, 2023).
Interstitial cardiac fibrosis (1 paper, 2017). A type of myocardial fibrosis characterized by excessive diffuse collagen accumulation concentrated in interstitial spaces. "In our recent study, we demonstrated that transgenic overexpression of SphK1 in mice resulted in interstitial cardiac fibrosis but not hypertrophy, which was mediated via S1PR3 but independent of AT1." (PMID 28771545, 2017).